INS (insulin)
Diseases named in the same sentence as INS in open-access papers (continued):
Sharing a sentence is not in itself a finding about the gene and the disease.
Nephropathy (continued). "It is a marker of kidney damage in both insulin-dependent and non-insulin-dependent diabetics, serving as an early indicator of nephropathy." (PMID 37692611, 2023). "In contrast, in the diabetic patients without the nephropathy group, these correlations were limited to fasting insulin and HOMA IR." (PMID 37831346, 2023). "In diabetic patients without nephropathy, there were significant (P < 0.001) positive correlations between serum hsa-miR-221 and fasting insulin (r = 0.537) and HOMA IR (r = 0.622) only." (PMID 37831346, 2023). "Even though some of the participants had kidney disease as a complication of DM, had DM for more than 30 years or were receiving insulin injections, they described that their state was not different from that of other older adults." (PMID 36655539, 2023). "Likewise, the proportions of nephropathy, HTN as well as phakic participants, were significantly higher in the insulin group." (PMID 35227220, 2022). "Reducing blood glucose in T1DM is necessary to avoid side effects such as neuropathy, glaucoma, nephropathy, and cardiomyopathy, for which the most popular treatment is insulin injection, although this is not very practical." (PMID 32489555, 2020). "Study cohort: the nationwide Veterans Administration Health Care System electronic medical records among 40‐89 years old men with T2D; without CLD, cancer, cardiovascular or renal diseases previously; insulin and thiazolidinedione naive." (PMID 30993905, 2019). "Studies have shown that insulin-sensitizing agents, including metformin and PPARγ agonists, are beneficial in preventing kidney damage in both T1DM and T2DM as well as in non-DKD." (PMID 29686650, 2018). "In this study, the contaminated tea infusion had an adverse effect on mice, including that blocking green tea-induced decreasing levels of ALT, TG, FFA, LDL, and increased INS level compared with obese mice and increasing the BUN and S-Cr levels which was indicated that it induced kidney damage." (PMID 29163391, 2017). "On the other hand, IR wouldn’t be higher in lean individuals (who had higher insulin doses) and our composite endpoint of nephropathy comprehends many individuals with mild or no renal disfunction." (PMID 27011769, 2016). "There are no restrictions on the use of insulin in patients with renal disease, and clinically significant reductions in renal insulin metabolism are uncommon in patients with eGFRs >20 mL/min/1.73 m2." (PMID 26239457, 2015). "Separate sub-group analyses for patients above and below an HbA1c of 63.9 mmol/mol (8%), patients without history of CV and renal diseases, and patients using MET/SU produced similar risk estimates for CV events in the EBID and EBID + insulin groups." (PMID 25616979, 2015). "18.9% of patients with nephropathy were using insulin, which is significantly higher than non-nephropathic patients, (p<0.0001)." (PMID 24586457, 2014). "In participants without renal disease fasting second-void UCPCR0 strongly correlated with serum insulin (rs=0.69, p<0.0001), C-peptide (rs=0.73, p<0.0001) and HOMA2-IR (rs=−0.69, p<0.0001)." (PMID 24353253, 2013). "The insulin therapy for tissues that do not require insulin does not prevent complications such as neuropathy, retinopathy, nephropathy, and cataracts." (PMID 22649481, 2012). "The higher prevalence of nephropathy observed in that study may be explained by the fact that most patients were not undergoing intensive insulin therapy." (PMID 40457148, 2025). "Without insulin, individuals with DM may experience persistent hyperglycemia, leading to complications such as microvascular issues (retinopathy, nephropathy) and macrovascular problems (heart attacks, strokes, and decreased blood flow to the legs)." (PMID 40005351, 2025). "Changes in patients’ conditions between visits, such as the initiation of insulin or lipid-lowering medications or the development of kidney disease, were not accounted for and could introduce bias." (PMID 39765929, 2024).
Nephropathy (continued). "The higher level of HbA1c and proportion of patients taking insulin with or without oral hypoglycemic agent(s) in cluster 3 showed simultaneous relationships between poorly controlled glycemia and other microvascular complications: retinopathy and nephropathy." (PMID 29387729, 2017). "The impact of kidney disease on insulin-mediated microvascular responses has not been studied and may contribute to a reduction in glucose uptake in the muscles under in vivo conditions." (PMID 28459862, 2017). "Tight glucose control, through intensive insulin therapy, in insulin-dependent individuals, delays, but does not eliminate, complications such as nephropathy, retinopathy, cardiovascular disorders, and various neurological problems, which greatly increase mortality and morbidity." (PMID 27070593, 2016). "Among patients without history of cardiovascular and renal diseases, compared to insulin group, patients in the EBID and EBID + insulin group had a 77% (HR CI: 0.06, 0.95) and a 55% (HR CI: 0.28, 0.85) reduced risk of MI, respectively, after adjusting for covariates." (PMID 25616979, 2015). "In general, insulin is prescribed for patients in whom OAD treatment failed, or one or more of the following concomitant diseases are present for which OAD treatment is contraindicated: OAD allergy, chronic liver or renal diseases, multiple organ failure, or some site-specific cancers." (PMID 23308218, 2013). "The reason why the use of oral hypoglycemic agents did not affect insulin dosage significantly in this study may be that the study population were composed of patients with kidney disease who had difficulty in controlling blood glucose and required a large amount of insulin." (PMID 40114703, 2025). "Third, circulating TG and insulin concentrations increased with CKD, and FPG was higher in participants with moderate to severe CKD than in those without kidney disease or mild CKD." (PMID 33297489, 2020). "In treatment-naïve, asymptomatic adults with T2DM and no overt CV or renal disease in whom HbA1cis > 9.0%, DUAL THERAPY including metformin and insulin-based therapy should be considered to improve blood glucose control." (PMID 32489427, 2020). "Among patients without CV disease history (n = 34,672) and without history of renal disease (n = 33,744), similarly reduced risks of HF were observed in EBID and EBID + insulin groups." (PMID 25616979, 2015). "Lifelong exogenous insulin administration is the standard treatment for T1DM; however, it is difficult to maintain physiological insulin levels, and therefore, this treatment is not very effective in alleviating T1DM complications such as retinopathy, nephropathy, and neuropathy." (PMID 36841925, 2023). "We excluded 17 RCTs for the following reasons: the dose used in the RCTs did not meet our criteria, open label extension with optional cross-over of placebo, included patients with kidney disease, was not double blind or assessed the combination of SGLT2-i and OAD or insulin." (PMID 27835680, 2016).
heart failure (439 papers, 2005 to 2026). Inability of the heart to pump blood at an adequate rate to meet tissue metabolic requirements. "Conversely, heart failure itself increases the risk of developing type 2 diabetes, likely due to shared mechanisms such as insulin resistance and systemic inflammation." (PMID 41008649, 2025). "Less REM sleep has been associated with cardiometabolic disease risk, including reduced insulin sensitivity, increased consumption of carbohydrates and fat, and heart failure and mortality." (PMID 40817294, 2025). "Phenylalanine and tyrosine have been shown to be associated with incident heart failure and to increase the risk of T2D by impairing both insulin secretion and insulin sensitivity." (PMID 41303064, 2025). "In the analysis of heart failure, SUs and acarbose were associated with a significantly lower risk (HR: 0.59 [95% CI 0.41–0.85] and 0.62 [95% CI 0.44–0.88]) compared to insulin." (PMID 40836299, 2025). "This duality is fundamental in heart failure patients on insulin therapy, which has been associated with arrhythmogenic risk." (PMID 40822953, 2025). "RyRs most likely play significant roles in a variety of functions and pathological conditions, such as in neurodegeneration, epilepsy, heart failure and associated skeletal muscle function impairment, insulin regulation, and epithelial function." (PMID 39099424, 2024). "The factors associated with hospitalization included being married, heart failure, falls, amputation, and insulin treatment." (PMID 39058533, 2024). "Impairments in insulin signaling among obese or diabetic patients are thought to contribute to their increased risk of heart failure." (PMID 39026321, 2024). "The inability of the heart to respond to insulin and appropriately alter the relative oxidation of fatty acids and glucose is associated with cardiovascular disease and heart failure." (PMID 38796064, 2024). "Adaptations to insulin signaling in obese or diabetic patients are believed to contribute to their increased risk of heart failure." (PMID 39026321, 2024). "Deficiency of the insulin signaling pathway leads to cardiac energy deficiency and accelerates the progression of heart failure." (PMID 37234159, 2023). "After excluding other systemic causes of edema such as heart failure, renal failure, and liver failure, a diagnosis of insulin edema was made." (PMID 38116161, 2023). "Heart failure is linked to many mitochondria-associated processes, including endoplasmic reticulum stress, mitochondrial bioenergetics, insulin signaling, autophagy, and oxidative stress." (PMID 37624101, 2023). "Heart failure is also associated with other mitochondrial processes such as endoplasmic reticulum stress, mitochondrial bioenergetics, insulin signaling, autophagy, and oxidative stress." (PMID 37624101, 2023). "Exogenous insulin use, to maintain glycemia has also been associated with an increased risk of heart failure." (PMID 36073057, 2022). "The five most important variables in the prediction models of all-cause mortality were age, BMI at enrollment, history of heart failure, insulin use, and smoking status." (PMID 35713855, 2022). "Such insulin abnormalities can also adversely affect cardiac function and serve as independent risk factors for incident heart failure (HF)." (PMID 35941584, 2022). "Heart failure is associated with an insulin resistant state, linked to the overactivation of the sympathetic nervous system." (PMID 35887892, 2022). "Insulin use, which is common in up to one-third of DM patients, is an independent risk factor for the development of heart failure and LV dysfunction." (PMID 35574440, 2022). "Poor glycemic control has been associated with increased risk for heart failure hospitalization, and the requirement for insulin in particular has been associated with an increased risk for adverse cardiovascular outcomes in this population." (PMID 35717169, 2022).
heart failure (continued). "The risk of incident heart failure associated with insulin was investigated in the ORIGIN (Outcome Reduction with an Initial Glargine Intervention) trial." (PMID 34097240, 2022). "Insulin use was also associated with a significantly increased risk of hospitalization for heart failure, even after adjustment for prior heart failure." (PMID 34158057, 2021). "Except the adverse effect of glucose dysregulation, the use of insulin and other oral anti-hyperglycemic drugs like TZDs have been associated with increased heart failure risk." (PMID 33335511, 2020). "Loss of insulin signaling pathway induced cardiac energy deficiency and accelerated the heart failure progress." (PMID 32460775, 2020). "Cardiomyocytes are insulin-responsive cells and impaired insulin-signaling are associated with heart failure." (PMID 31936892, 2020). "Insulin causes sodium retention and hypoglycaemia and its use is associated with worse outcomes in heart failure (HF) with reduced ejection fraction." (PMID 31271255, 2019). "Some researchers have suggested not only that the heart is a target organ of systemic insulin resistance, but also that local myocardial insulin resistance is a distinct risk factor for heart failure." (PMID 31461405, 2019). "This sub study of a randomized, phase II/III trial failed to observe any additional cardioprotective effect of iv exenatide compared to iv insulin following CABG surgery in a population of patients at low risk of post-operative heart failure." (PMID 30384842, 2018). "For example, insulin-supplement therapy has recently been reported to significantly be associated with patient mortality in elderly patients with heart failure." (PMID 29888270, 2018). "Mechanically, the weight loss-related to heart failure has been explained as part of its metabolic impairment, namely insulin resistance, global anabolic blunting and catabolic overactivity due to catecholamine, TNF-alpha, and natriuretic peptides release." (PMID 29075334, 2017). "Early stages of heart failure have been associated with significant reductions in insulin sensitivity and consequently, compromised glucose homeostasis." (PMID 27375480, 2016). "Monotherapy with sulphonylureas was also associated with an increased risk of cardiovascular disease and as triple treatment with metformin and insulin was associated with an increased risk of heart failure compared with metformin alone." (PMID 27413012, 2016). "Triple treatment with sulphonlyureas, metformin, and insulin was associated with a 42% increased risk of heart failure." (PMID 27413012, 2016). "Heart failure with left ventricular (LV) hypertrophy is often associated with insulin resistance and inflammation." (PMID 24521405, 2014). "The study showed that treatment with metformin was associated with a low risk of mortality in diabetic patients with heart failure compared with treatment with SU or insulin." (PMID 23574917, 2013). "Insulin therapy is potentially associated with an increase in all-cause mortality, especially in patients with heart failure." (PMID 22509138, 2012). "In the present study we find a relationship between CFR, VO2peak and insulin sensitivity, which also are well known prognostic risk factors in heart failure, suggesting that these risk factors are closely linked." (PMID 22889317, 2012). "This is the first study to our knowledge that shows an association between CFR and exercise capacity in heart failure patients and links the relationship between insulin resistance and exercise capacity to CFR." (PMID 22889317, 2012). "In our study, patients exposed to TZDs were less likely to present risk factors of heart failure and cardiovascular comorbidities, 5.6% had a cardiac insufficiency, and less than 3% were treated concomitantly with insulin." (PMID 21609444, 2011). "Additional adverse effects associated with TZDs used for insulin sensitizing therapy include edema, weight gain, macular edema, and heart failure." (PMID 20204067, 2010).
heart failure (continued). "Other considerations include the risk of heart failure, fractures in women, a reduced insulin dose, and the net financial cost." (PMID 19568428, 2009). "For instance, insulin secretagogues may induce hypoglycemia, biguanides can provoke gastrointestinal distress, and thiazolidinediones may elevate the risk of heart failure." (PMID 40647154, 2025). "Among high‐risk, insulin was most prevalent in those with heart failure or chronic kidney disease." (PMID 40464139, 2025). "Biological studies examining the effects of aripiprazole on sympathetic activity, insulin signaling, and cardiac myocyte function could shed light on why heart failure risk might be elevated." (PMID 40792205, 2025). "A prominent example includes fluid retention caused by antidiabetic drugs that may increase the possibilities of heart failure or increase body weight associated with insulin therapy, which can be linked to a higher risk for ischemic stroke." (PMID 39407846, 2024). "However, recent evidence showed that insulin use is associated with poor outcomes in the context of heart failure (HF)." (PMID 37542280, 2023). "Furthermore, a reduced whole-body insulin sensitivity has been shown to be an independent prognostic cardiovascular risk factor in patients with heart failure." (PMID 36624469, 2023). "But as a potential risk factor, excessive activation of insulin signaling pathway may worsen heart failure." (PMID 35308248, 2022). "Ca2+ handling dysfunction is a well-defined hallmark of heart failure, and it has long been hypothesized that elevations of cytosolic free Ca2+ in insulin-targeted cells may lead to the development of insulin resistance." (PMID 37583938, 2022). "Another class of drugs which may raise the risk of AEs when combined with insulin are thiazolidinediones because of their risk of oedema and heart failure." (PMID 33098260, 2021). "Thiazolidinediones can cause bladder cancer and fractures, and combined insulin-thiazolidinediones therapy may lead to heart failure." (PMID 32982969, 2020). "Combined with our prior findings of increased expression of Ptprf, a transcriptional change associated with decreased sensitivity to insulin signaling, this suggests a potential role for metabolic dysregulation as a causal link between in utero DE exposure and adult susceptibility to heart failure." (PMID 30975218, 2019). "In this study, we examined insulin sensitivity in the hypertrophic heart to determine whether cardiac insulin resistance is an independent risk factor for heart failure." (PMID 31461405, 2019). "Heart failure is often associated with impairment in insulin signaling which could have a marked impact on energy metabolism in the heart." (PMID 29928647, 2018). "However, this is countered by evidence from several studies in which diabetic patients on insulin therapy exhibit increased risk of developing heart failure." (PMID 29867503, 2018). "However, studies indicate that partial PPARγ agonists have lower risks of causing side effects (e.g., edema, fractures, and heart failure) relative to full PPARγ agonists, although they exhibit similar effects associated with insulin sensitivity." (PMID 30627576, 2018). "Furthermore, elevated levels of glucose and insulin in the blood can activate the sympathetic nervous system, which has been implicated in the development of heart failure." (PMID 26392171, 2015). "Screening programs should address the assessment of diastolic function and therapeutic options capable of improving insulin sensitivity might be considered in the treatment of these patients at risk for the development of heart failure." (PMID 20950415, 2010). "Furthermore, insulin co-administration with other medications (e.g., pioglitazone) may synergistically increase heart failure risk." (PMID 40647154, 2025).